ENSG00000206961
Synonyms: LOC124900531
Gene: Small nucleolar RNA gene on chromosome 2 (169,727,872 to 169,728,003, forward strand). Ensembl gene ENSG00000206961.
Gene Ontology:
Biological process: RNA processing
Cellular component: nucleolus
Homologues: Orthologues: rat LOC120100392 (74% identical). Paralogues in human: SNORA51 (84% identical).